CCL5 (C-C motif chemokine ligand 5)
Diseases named in the same sentence as CCL5 in open-access papers (continued):
Sharing a sentence is not in itself a finding about the gene and the disease.
tumor (continued). "Recruited by tumour-derived chemokines such as CCL2, CCL5, and CCL8, TAMs are reprogrammed to enhance EMT, tumour motility, and metastasis, while hampering T-cell infiltration." (PMID 40361472, 2025). "Activation of this pathway results in the release of chemokines such as CCL5, CXCL9, and CXCL10, which recruit immune cells—including CD8+ T lymphocytes, macrophages, and dendritic cells—into the tumour microenvironment." (PMID 40596709, 2025). "During tumor development, inflammatory signals recruit macrophages to the tumor stroma, including chemokines (e.g., CCL2, CCL5, CXCL12), cytokines (e.g., VEGF, CSF1), and complement factors." (PMID 40872551, 2025). "Another study illustrated that TNBC cells activate the IL-6-STAT3 signaling pathway, which increases levels of the chemokines, VEGF, and chemokine (C-C motif) ligand 5 (CCL5) and encourages lymph node angiogenesis and lung extravasation of tumor cells." (PMID 40933989, 2025). "Tumor cells secrete chemokines like CCL2, CCL5, and CSF-1 that recruit monocytes from the bloodstream into the TME, where they differentiate into TAMs." (PMID 39930476, 2025). "ELISA results indicated higher IFN-β, CCL5 and IFN-γ levels, revealing enhanced tumor immunomodulation after the combined treatment." (PMID 40355720, 2025). "This process requires the production of appropriate chemokines by the endothelial cells and tumor stroma, namely CXCL9, CXCL10, CXCL11, and CCL5." (PMID 41008910, 2025). "Some of them, such as CCL5, CXCL10, and CXCL9, are produced by DCs upon activation to favor tumor T cell recruitment." (PMID 40578365, 2025). "The results were consistent with our expectations: CCL5, LOX, and C3 were significantly upregulated in tumor tissues, whereas PLG exhibited markedly higher expression in normal tissues." (PMID 40396123, 2025). "CAAs play an essential role in promoting tumor progression by secreting multiple adipokines, such as CCL2, CCL5, leptin, and adiponectin." (PMID 40248695, 2025). "In the tumor microenvironment, chemokines such as CCL2, CCL3, CCL4, and CCL5 attract monocytes that differentiate into TAMs." (PMID 39941858, 2025). "This insufficient vascularization is often accompanied by low levels of chemokines such as CCL4, CCL5, and CCL20, which are essential for recruiting dendritic cells to the tumor site for effective antigen presentation." (PMID 41149836, 2025). "NK cells secrete cytokines and chemokines, such as CCL5, XCL1, and XCL2, which promote dendritic cell migration into solid tumors, and enhance the anti-tumor activity of CD8+ T cells." (PMID 40657373, 2025). "Specifically, nuclear FAK promotes immune evasion through increased CCL5 expression to drive exhaustion of CD8+ T cells and recruit regulatory T cells (Tregs) in the tumor microenvironment." (PMID 40458728, 2025). "Proinflammatory chemokines typically produced by DCs to promote the recruitment of T cells, such as CCL5, CXCL9, and CXCL10, were increased in the tumor microenvironment of mice treated with the combination." (PMID 40578365, 2025). "Cytokine profiling revealed significantly elevated levels of CCL5, IFN-β, and IFN-γ in both tumor tissues and serum of H62-treated mice, consistent with an enhanced systemic and local immune response." (PMID 41239499, 2025). "Through high-throughput screening, verteporfin has been identified as a potent antagonist of the CCL5/CCR5 axis, demonstrating the ability to inhibit tumor growth in TNBC through immunomodulation." (PMID 40303301, 2025). "For example, an excess of the chemokine CCL5 increases antigen-specific CD8+ T cells, which exert anti-tumor immunity." (PMID 40092490, 2025). "Previous research showed that pericytes facilitate the resistance to temozolomide by releasing CCL5, which binds to the chemokine receptor CCR5 on tumor cells, triggering the DNA-PKcs/AKT pathway to enhance DNA repair and diminish cell death." (PMID 40565309, 2025).
tumor (continued). "Stabilized c-Myc in turn represses CCL5 expression, reducing CD8+ T-cell recruitment into the tumor microenvironment." (PMID 41373479, 2025). "MSC2: Secretion of CCL5, TGF‐β, IL‐6, VEGF, IL‐8, IL‐10, MMPs (Induction of angiogenesis, metastasis, enhanced tumor stemness, immunosuppression, differentiation into CAF)." (PMID 40150879, 2025). "Our data suggest that PTE remodels the tumor microenvironment (TME) by activating STING-mediated signaling, leading to increased chemokine production (e.g., CXCL10, CCL5) and enhanced CD8+ T-cell recruitment and function." (PMID 41181138, 2025). "Subsequently, we examined the mRNA levels of CCL5, CD274, CXCL10, CXCL11, and CCL2 in MDA‐MB‐231 and 4T1 cells and tumor tissues." (PMID 39585774, 2025). "Chemokines including CXCL5/CXCR2 are essential for MDSC recruitment in 4T1 BALB/c murine tumor models, while CCL1, CCL2, CCL5, GM-CSF, and G-CSF facilitate MDSC expansion and aggregation in the tumor milieu." (PMID 40909271, 2025). "It is known that PBMC recruitment plays essential roles in tumor progression and metastasis and that cancer cells are able to recruit them by secreting several chemokines, such as CCL2, CCL3, CCL4, and CCL5 among many others." (PMID 40112045, 2025). "NK cells produce chemoattractants, such as CCL5 and XCL1, that recruit cDC1s to tumor sites, meanwhile, tumor-derived factors, such as PGE2, can suppress NK cell viability and chemokine production." (PMID 40165899, 2025). "Activated tumor-infiltrating eosinophils produce high levels of chemokines, such as CCL5, CXCL9, and CXCL10, which attract co-metastatic CD8 + T cells to the tumor, leading to tumor rejection and prolonged survival." (PMID 39141277, 2025). "CCL5 signals through its cognate receptor CCR5 to promote tumor growth, tumor progression, tumor cell migration and metastasis." (PMID 40070829, 2025). "The inhibitors targeting HIF-1α also can inactivate the tumour microenvironment-derived extrinsic signals (CSF1 and CCL5) to further improve the response of targeting intrinsic molecular pathways to overcome the resistance to anti-VEGF therapy." (PMID 39267775, 2024). "To achieve this, we measured the levels of chemokines (CCL5, CXCL9, and CXCL10) in tumor tissues using ELISA across different treatment groups." (PMID 38931345, 2024). "For instance, CCR4/5 and CXCR3, expressed by CD8+ T cells, allow their ligands CCL5, CXCL9, and CXCL10 to guide the migration of CD8+ T cells into tumor tissue." (PMID 39769501, 2024). "One of the resultant effects is an increased expression of the chemokines CCL5 and CXCL10, resulting in T-cell recruitment and an enhancement of lymphocyte function in the tumour." (PMID 39796639, 2024). "In the invasive margin of CRC liver metastasis (CRC-L), CCL5+CD4 and CD8 cells, recruited by myeloid-derived CXCL9 and CXCL10, attract macrophages promoting invasion and tumor growth by MMP." (PMID 39100682, 2024). "The CCL5/CCR5 axis plays a role in the immune microenvironment and is exploited to facilitate tumor progression." (PMID 39199626, 2024). "Monocytes are recruited in to the tumor site and differentiate into macrophages upon tissue infiltration, and this process is mediated by inflammatory signals such as CCL2, CCL5, and CSF-1 secreted by tumor cells and other cells within the malignant TME." (PMID 38730724, 2024). "The promotion of monocyte CCR5 surface expression by EBV-positive tumour cell CM correlated with an enhancement of the macrophage modulatory factor towards CCR5-chemokines, CCL5." (PMID 39267775, 2024). "Nevertheless, HCC displays a more immunosuppressive TME due to Tregs, MDSCs, intrinsic tumor features (CXCR4, CCL5, arginase) and the contest in which it develops." (PMID 37142825, 2024). "In order to recruit macrophages into the TME, tumor cells secrete various chemokines, including CSF-1, CCL2, CCL5, CX3CL1, and CXCL12." (PMID 38341519, 2024).
tumor (continued). "CCL5, CXCL1, CXCL2, CXCL5, and CXCL12 are chemokines produced by senescent cells that have opposite effects on tumor development." (PMID 39007138, 2024). "Further studies are warranted for analysing the potential value of CCL5, CXCL9 and IFN-ɣ as biomarkers of response to trastuzumab-deruxtecan and the possible synergism between trastuzumab-deruxtecan and tumor-infiltrating NK cells." (PMID 38167224, 2024). "SNAIL expression in tumor cells increases their secretion of CCL2, CCL5, and CXCL2, all of which attract macrophages to the TME." (PMID 39555068, 2024). "BRAF mutations can lead to the secretion of various cytokines and chemokines (such as CCL2, CCL5, and CXCL8) by tumor cells, altering the surrounding tumor microenvironment." (PMID 39529955, 2024). "Specifically, CCL5 promotes the infiltration of regulatory T cells (Tregs) into the TME, thereby favoring tumor growth." (PMID 39507529, 2024). "In vitro, both pharmacological inhibition and genetic targeting of VPS34 enhance cGAS-STING-mediated expression and secretion of CCL5 and CXCL10 across various tumor cell types." (PMID 40395527, 2024). "It was found that CCR5 antagonists can disrupt TAM recruitment via the CCL5/CCR5 pathway, enhancing the clinical outcomes for various cancers, including gastric and pancreatic, by curbing tumor progression and extending patient survival." (PMID 38341519, 2024). "Ligands such as CCL5, CCL7, and CXCL8 released by tumor cells bind to receptors CCR1 and CXCR2 expressed on MDSC, causing them to cluster and migrate chemotactically towards the TME." (PMID 39660124, 2024). "Additional chemo-/cytokine analyses from co-culture supernatants of THP-1-macrophages and pre-treated tumor cells show an increased inflammatory response upon combination treatment, e.g. for chemoattractants CCL4 or CCL5." (PMID 38357194, 2024). "BC cells, in addition to other immunosuppressive cells secrete PGE2 which can reduce the presence of tumor-infiltrating NK cells and inhibit NK cells production of XCL1 and CCL-5." (PMID 39609700, 2024). "In the tumor microenvironment, CCL5 promotes cancer progression implying a connection between YBX1 and tumor-promoting inflammation." (PMID 38255791, 2024). "The secreted CCL5 binds to CCR5, the CCL5 receptor, which promotes TNBC tumor growth and metastasis to lymph nodes." (PMID 38393465, 2024). "CCL5 was mainly expressed in the tertiary lymphoid structure (TLS), whereas CYP1A1 was predominantly expressed in the remaining active tumor cells, especially those adjacent to TLS." (PMID 39183447, 2024). "This suggests that CCL5, which was upregulated in LM4 tumor tissues, is secreted from TME component cells such as CAFs, which were also upregulated in LM4 tumor tissues upon immunohistochemical analysis." (PMID 39126553, 2024). "Our results showed that PARP/HDACi treatment augmented the mRNA levels of CCL5 and CXCL10 in three different TNBC cell lines and MDA-MB-436 tumor-bearing mice." (PMID 38182579, 2024). "Fibroblast clones secrete IL-6, IL-8, NFkB, IFN-y, HGF, CTGF, CCL5, and PGE5 to promote tumour growth." (PMID 39046819, 2024). "For example, CCL5 produced by tumor cells or CXCL9 and CXCL10 also expressed by tumor-resident myeloid cells determine effector T-cell recruitment to the tumor microenvironment." (PMID 39669575, 2024). "We are very cautious about the CCL5 elevation in the OPT group in the 12th month, because the CCL5/CCR5 axis is suspected to facilitate tumor progression." (PMID 38673624, 2024). "The CosMx data also revealed that C1QC+ macrophages, CCL5+ T cells, and IGHG1+ plasma cells were more abundant near one tumour subclone while COL3A1+ fibroblasts were more abundant near the other." (PMID 38570491, 2024). "IHC and mIHC further exhibited the increased infiltration of CD8+CCL5+ T cells after treatment, leading to an upregulated expression of CYP1A1 in residual tumor cells." (PMID 39183447, 2024).
tumor (continued). "Crucially, MDSCs are recruited to tumor sites via various chemokine axes, such as CCL8/CCR2, CCL5/CCR5, CXCL5/CXCR2, and CXCL12/CXCR4." (PMID 39769501, 2024). "A substantial body of research substantiates that CC chemokines (e.g., CCL2, CCL5) and CXC chemokines (e.g., CXCL1, CXCL2, CXCL5) recruit diverse immune cells, such as CCR2+ monocytes and CXCR2+ neutrophils, to tumor sites." (PMID 39206194, 2024). "Previous data suggest that once pIRF3 enters the nucleus, it activates the type I IFN response, consequently stimulating the secretion of chemokines, Chemokine (C-C motif) ligand 5 (CCL5), and C-X-C Motif Chemokine Ligand 1 (CXCL10) in tumor cells." (PMID 38169513, 2024). "It has been shown that CCL5 recruits Tregs via CCR5 and stimulates TGF-β to block the tumor killing function of CD8+ T cells." (PMID 39329710, 2024). "Bidirectional crosstalk between tumor cells and CAFs enhances the ability of fibroblasts to secrete various pro-tumor chemokines, including CXCL12/CXCR4 axis, CCL2, CCL5, CCL7, CXCL8, and CXCL14." (PMID 39092186, 2024). "Relative to vehicle (PBS)-treated controls, NFκB inhibition reduces tumor proliferation (%Ki67+ cells), BLBP+ and Olig2+ cells (%Olig2+ and %Blbp+ cells) and Ccl5 expression at 12 weeks of age." (PMID 38308315, 2024). "Correlation analysis of the expression of CCL5, CCR5, and CYP1A1 in tumor tissues after combination therapy revealed a certain degree of correlation among them." (PMID 39183447, 2024). "The suppression of CCL5 expression by heat shock Factor 1 (HSF1) prevents CD8+ T-cell influx, which supports immune-mediated tumor killing." (PMID 38928033, 2024). "As verified by exocytotic chemokines, the expression of tumor-promoting chemokines, including CCL3, CCL5, CCL7, CCL11, CXCL1, and CXCL12, showed a downward trend after MWA." (PMID 38779358, 2024). "This study shows that Natural Killer cells that infiltrate the tumor (TI-NK) produce CCL5 and IFN-ɣ upon activation, triggering the development of an effective anti-tumor immune response along anti-HER2 antibody-based neoadjuvant treatment." (PMID 38167224, 2024). "Together, these findings support the idea that APG-2575 has an important effect on enhancing CCL5- and CXCL10-mediated CD8+ T-cell recruitment into the TME to promote tumor regression." (PMID 38062129, 2024). "A major tumor-promoting role for the coexpression of the chemokines CCL2 and CCL5 in tumor cells has been suggested in breast malignancies." (PMID 38928033, 2024). "Silencing CCL5 expression in Panc02 cells or systemic administration of the CCR5i TAK-779 reduces Treg migration and tumor volume in a murine subcutaneous tumor model." (PMID 39656086, 2024). "Under the combined influence of hypoxia and cytokines, such as CCL2, CCL5 and CSF1–-produced by tumor cells, fibroblasts, endothelial cells, or TAMs themselves, macrophages will be largely recruited to hypoxic tumor compartments." (PMID 39175095, 2024). "In a recent study, Tregs were also found to mediate the CCL5/CCR5 promotion of BC axillary lymph node metastasis in peripheral blood and tumor tissue cells from BC patients analyzed by flow cytometry." (PMID 39329710, 2024). "The mRNA expression of CCL5, CCR5, and CYP1A1 in tumor specimens from surgery after combination therapy was significantly higher than that in tumor tissues from direct surgery." (PMID 39183447, 2024). "Tissue experiments showed that after combination therapy, the CCL5/CCR5/CYP1A1 pathway was activated, which can benefit the residual tumor cells to survive treatment." (PMID 39183447, 2024). "As previously acknowledged, CCL5 and CXCL10 as pivotal signaling bridges between NK cells and T cells, and tumor cells." (PMID 38550593, 2024). "We found that in the low-score group, ARHGAP15 tumour cells and CD8 + CCL5 immune cells were significantly colocalized, indicating good spatial consistency, according to the spatial transcriptome sequencing (ST-seq) data." (PMID 38730464, 2024).
tumor (continued). "In CCA, TAMs can promote tumor progression through various pathways, such as the SHH/GLI2/TGF-β1 pathway and the aPKCγ/CCL5 pathway, as previously summarized." (PMID 39290697, 2024). "To understand the cause of CCL5-mediated reduced survival in PDAC, we hypothesized that immune cells responsive to a CCL5 chemotactic gradient (through expression of the cognate receptors CCR5, CCR3, or CCR1) could be potential contributors to an adverse tumor immune environment." (PMID 39656086, 2024). "CC-chemokine ligand (CCL) 2, CCL5, and CCL18 and transforming growth factor beta (TGFB) 1 secreted by tumor cells have been described to have chemotactic effects on macrophages." (PMID 39272860, 2024). "It has also been observed that inter-tumoral MDSCs produce high amounts of CCL-3, CCL-4, and CCL-5, which can attract CCR5+ T-regs to the tumor site." (PMID 39609700, 2024). "CCL5/CCR5, on the other hand, affects the efficacy of tumor therapy mainly by promoting inflammatory responses as well as inducing the adherence and migration of different T cell subsets involved in the immune response." (PMID 39075190, 2024). "CC chemokine ligand 5 (CCL5) and CC chemokine receptor 5 (CCR5) were not only the leading players in tumor progression but also exerted anti-tumor immunity by recruiting T cells and dendritic cells, enhancing immunotherapy responses of multiple tumors." (PMID 39723215, 2024). "Another way by which HSF1 helps tumor cells to evade immune surveillance is by suppressing the expression of CCL5, a CD8+ T-cell chemokine, thereby inhibiting the recruitment and infiltration of CD8+ T-cells into the tumor microenvironment." (PMID 39682216, 2024). "Consistently, quantification of activated natural killer (NK) cells and CD8+ T cells in the metastatic liver showed that they were also preferentially enriched at the tumour margin, next to KCs expressing CCL3, CCL4, CCL5, IL-12, IL-15 and IL-18." (PMID 38326607, 2024). "CCL5 is an important chemokine that recruits PMN-MDSCs to tumor sites and promotes the proliferation of CCR5+ PMN-MDSCs in the BM, greatly supporting tumor development." (PMID 38786066, 2024). "In LUAD patient tumor samples, we confirmed a positive correlation between MIR155HG, CCL5, CD8, and PD-L1 expression." (PMID 39043648, 2024). "In tumor regions, the expression levels of CCL2, CCL5, CCL20, CXCL9, CXCL10, CXCL11 and CXCL12 were generally higher in hot tumors than in the other two groups." (PMID 37847338, 2024). "Nevertheless, the CCL5/CCR5 axis, which is anticipated to recruit immunosuppressive macrophages, remained prominent in this combo-treated tumor." (PMID 39298276, 2024). "The mRNA levels of the cytokines CCL5, CCL18, and GDF15, as well as the transcription factor IRF4, showed a positive correlation with the tumor volume." (PMID 39272860, 2024). "The IHC results showed upregulated expression of CCL5, CCR5, and CYP1A1 in tumor samples from patients following combination therapy." (PMID 39183447, 2024). "Immunofluorescence staining in tumour-bearing liver from KPC mice and littermate controls confirmed that the CCR5 ligands CCL3, CCL4 and CCL5, and the cytokines IL-12, IL-15 and IL-18 were produced by KCs in peritumoural liver." (PMID 38326607, 2024). "At the same time, extracellular tumor-promoting chemokines, such as CCL3, CCL5, CCL7, CCL11, CXCL1, and CXCL12, were also downregulated." (PMID 38779358, 2024). "In keratinocytes, the activation of FFAR1 receptors by GW9508, an FFAR1 and FFAR4 agonist, reduced the release of several chemokines, such as CCL5 and CCL17 (C-C motif chemokine ligands 5 and 17), and attenuated skin immune inflammation." (PMID 39519187, 2024). "CCL5 and TGFB1 CSF concentration was moderately to strongly negatively correlated with tumor volume, as well as with Koos grade." (PMID 39272860, 2024). "The release of CCL5 and CXCL10 is essential for recruiting cytotoxic immune cells into the tumor microenvironment and enhancing the efficacy of cancer immunotherapy." (PMID 40395527, 2024).